RN7SL211P (RNA, 7SL, cytoplasmic 211, pseudogene)
Gene: Miscellaneous RNA gene on chromosome 2 (64,906,863 to 64,907,138, reverse strand). Ensembl gene ENSG00000244534.
Homologues: Orthologues: chimpanzee Metazoa_SRP (97% identical). Paralogues in human: RN7SL1 (76% identical), RN7SL2 (76% identical), RN7SL664P (76% identical), RN7SL709P (75% identical), RN7SL3 (75% identical), RN7SL448P (75% identical), RN7SL126P (75% identical), RN7SL543P (75% identical), RN7SL341P (74% identical), RN7SL50P (74% identical), RN7SL43P (74% identical), RN7SL45P (74% identical), and 701 more.